CD68 (CD68 molecule)
Diseases named in the same sentence as CD68 in open-access papers (continued):
Sharing a sentence is not in itself a finding about the gene and the disease.
cancer (continued). "We then checked the expression of the canonical cell-type markers: cancer/epithelial cell marker genes (Cdh1, Krt18, and Krt5); mesenchymal cell marker genes (Col1a1, Col1a2, and Col3a1); immune cell marker genes (Ptprc, Cd68, and Csf1r); and endothelial cell marker genes (Pecam1, Emcn, and Cdh5)." (PMID 34497807, 2021). "Based on these results, we subsequently focused on NKT cells and CD68+ macrophages and their potential interactions with other immune cells and cancer cells, whereby a potential interaction event was defined as the presence of a cell within a 15 μm radius of a reference cell." (PMID 33013928, 2020). "High expression of CD8+ PD-1High is associated with CD68+ PD-L1+, suggesting that CD68+ PD-L1+ could cooperate with CD8+ PD-1High to cause the suppression of anti-cancer immunity." (PMID 33228682, 2020). "Importantly, we noticed that p-Smad2 also is present in the nearby CD68- cancer cells (within dash line)." (PMID 32724475, 2020). "This assay confirmed the enrichment of macrophage (CD11b+CD68+) in cancer tissue." (PMID 30894509, 2019). "CD68 has been widely accepted as a specific marker of TAMs in human cancer." (PMID 31521128, 2019). "However, a large concentration of CD68 was observed at the site close to the cancer parenchyma where SHH expression was strong." (PMID 31744214, 2019). "In addition, some studies also evaluated the correlation between the ratio of CD163- to CD68-positive macrophages and clinicopathological features in malignant tumors." (PMID 31528210, 2019). "The association between high co-expression and co-localization of MMP-9/CD163/CD68 and poor survival in ER+ cancers suggests that these cancers may be candidates for macrophage-targeted therapies." (PMID 30558648, 2018). "High expression of MMP-9 in the CD68+/CD163+ TAMs was associated with worse OS in ER+ tumors (P <0.001) but not in ER− cancers." (PMID 30558648, 2018). "Furthermore, the ratio of Gal3 expressing cells and CD68 positive macrophages was significantly higher in lymph nodes of T2 carcinomas." (PMID 30115022, 2018). "While further work is required, our study suggests that the CD169+ cell density and the proportion of CD169+ to CD68+ macrophages in RLNs might be useful for examination of the status of anti-cancer immune responses." (PMID 27861544, 2016). "Moreover, we reported that patients with a higher CD169+ cell number or higher CD169+/CD68+ macrophage ratio in RLNs had a better clinical prognosis than those with lower levels of CD169+ cells in those cancers." (PMID 27861544, 2016). "High numbers of CD68+ TAMs were associated with an advanced pT category and high-grade cancer, acting as an additional independent factor (CD68/CD3 ratio > 1) with a more than 7-fold higher risk of cancer-specific death on multivariate analysis." (PMID 27221038, 2016). "CD68‐positive staining was positively correlated with advanced‐stage cancer (P = 0.002)." (PMID 26843477, 2016). "Finally, only a small number of cases showed the presence of macrophages (CD68) within cancer nests, with a score of 2; they were more prevalent in the stroma and even more so in the invasive margin in comparison to the other localizations." (PMID 27689405, 2016). "In addition, a greater number of CD68+ cells were observed in the mucosa adjacent to the carcinoma, as compared with the carcinoma tissue itself." (PMID 25434400, 2015). "To determine whether the expression of Bmi1 in cancer cells correlates with the levels of TAMs, we examined Bmi1, CD68, and CD163 expression in gastrointestinal cancer tissues using IHC." (PMID 24312366, 2013). "We found that, regardless of the overall MUC2 expression level, the density of CD68+COX-2+ TAMs was significantly higher in the cancer islets, in which MUC2 molecules were vigorously secreted, than in the stromal regions, in which MUC2 molecules were scarcely secreted (p<0.001, ANOVA)." (PMID 24324582, 2013).
cancer (continued). "Additionally, in the whole section (cancer islet+stromal region), the mean ratio of CD68+COX-2+ TAMs/total CD68+ TAMs was significantly higher in the high MUC2 expression group than in the low MUC2 expression group (p<0.001, Student’s t test)." (PMID 24324582, 2013). "Moreover, either in the cancer islets or in the stromal regions, the density of CD68+COX-2+ TAMs was significantly higher in the high MUC2 expression group than in the low MUC2 expression group (p<0.001, ANOVA)." (PMID 24324582, 2013). "Additionally, the observed correlations with immune checkpoints may reflect functional crosstalk - CD68+ macrophages in different cancers may exhibit distinct capacities for PD-L1 induction or cytokine secretion that shape these relationships." (PMID 40918116, 2025). "Moreover, we explored various small molecules and predicted drugs that target CD68 in pan-cancer." (PMID 35550532, 2022). "AIF-1 has been found to co-localize with CD68+ macrophages in human atherosclerotic coronary arteries, renal interstitium, and synovial membrane, being considered a marker of activated macrophages and endowed with prognostic value for inflammation-related diseases including cancer." (PMID 36520870, 2022). "Therefore, the blockade of TIM-3 on CD14+CD68+CD163+ macrophages might improve cancer immunosuppression." (PMID 36293034, 2022). "In addition, Gottfreid and colleagues studied the expression of CD68 in different primary cells and cancer cell lines, and found that CD68 expression was widespread, including monocytes, macrophages, fibroblasts, endothelial cells and even some cancer cells." (PMID 27144518, 2016). "Notably, cancer cells also express the macrophages antigen CD68 and CD163." (PMID 26769084, 2016). "In addition, the COX-2+ cells in the cancer tissue sections accounted for 3%-13% of all the observed M1 TAMs (i.e., CD68+ HLA-DR+ or CD68+ iNOS+ cells), and accounted for 93%-100% of the M2 TAMs observed (CD68+ CD163+ or CD68+ VEGF+)." (PMID 24324582, 2013). "Among the validated substrate candidates are the cancer-related ERBB2 as well as the immune system-related CD2, CD68, and CD86." (PMID 40593564, 2025). "Indeed, CD68‐positive CD169‐negative macrophages occupied significantly longer SCSs in the distal node, but this might be a result of the delayed “mobilization” of alveolar macrophages by local inflammation associated with cancer." (PMID 40151162, 2025). "In contrast, in SCLC, that was lately described as a cancer with a predominantly macrophage-rich TME, CD70 expression has a strong representation from CD68 + TAMs, and the molecule’s coexpression on T- or B-cells is not prevalent." (PMID 40205178, 2025). "In conclusion, our study establishes CD68 as both a prognostic biomarker and therapeutic target in DSC, with distinct clinical implications across cancer types." (PMID 40918116, 2025). "Key hub genes including CD68 in BRCA, CD74 in CRC and OVCA, and TIMP1 in LUSC, played critical roles in immune-cancer cell interactions and tumorigenesis inhibition." (PMID 41370198, 2025). "In CRC samples, higher levels of myeloid cell CCR2 were seen in tumors harboring mismatch repair deficiency/microsatellite instability–high than in microsatellite stable carcinomas, and this difference was predominant when measuring CCR2 in CD68+ TAMs." (PMID 39918395, 2025). "ART-treated mice showed increased CD68 and reduced CD56 expression, suggesting an immunosuppressive profile and higher carcinoma incidence." (PMID 40943044, 2025). "The density of TAMs decreased with each progressive cancer stage, and locoregional cancers (stage I–III) had a higher density of CD68+ TAMs than cancers with distant metastasis (stage IV) irrespective of CD163 expression." (PMID 38407700, 2024). "Among these cell type markers of cell clusters, cancer cell cluster specifically expressed keratin 19 (KRT19) and CEA cell adhesion molecule 1 (CEACAM1), and TAM cluster expressed CD68, CD163, and complement C1q C chain (C1QC)." (PMID 38302412, 2024).
cancer (continued). "CD68 is a commonly used marker to detect M2-like TAMs in the TME, which have been shown to promote cancer growth and metastasis through various mechanisms, including immune suppression and angiogenesis." (PMID 38357542, 2024). "Forced MALAT1 expression in cancer cells and xenograft models led to increased cell growth, invasiveness, and movement, along with higher levels of MCP-1, CD68, CD163, CD206, and KI67." (PMID 38791954, 2024). "We found that CD68, TNFα, and OTUD1 expression was inversely correlated with the overall survival of cancer patients." (PMID 37872170, 2023). "We performed a series of in-depth analyses of single cell RNA sequence data to characterise the origin of the cells identified by CD68 and/or CD163 positivity in cancer tissue." (PMID 36724681, 2023). "On the other hand, proinflammatory CD68+ M1 macrophages are known to have antitumor effects, producing pro-inflammatory cytokines such as TNF-α to induce cancer cell apoptosis." (PMID 38037106, 2023). "We then aimed to investigate the prognostic value of COMP expression levels in CRC tumors corrected for PD-L1 expression by immune cells and cancer cells, and the different markers of immune cells populations (CD3+, CD8+, FoxP3+, CD68+, CD56+, and CD163+)." (PMID 37207219, 2023). "We observed a higher number of macrophages (CD68) (P = 0.0001) and T lymphocytes (CD3) (P = 0.002) in SAT of cancer patients vs. controls, and the number of T lymphocytes was higher in cachectic vs. non‐cachectic patients (P = 0.025)." (PMID 34939367, 2022). "M2 macrophage markers such as CD163, CD68, CD206, and CD204 are TAM markers that are widely used to assess cancer progression." (PMID 36077342, 2022). "We therefore determined the infiltration of CD68+ and MAC387+ TAMs in HCMV- and HCMV+ cancer tissues of IBC patients." (PMID 35847899, 2022). "Here, we quantified MFG-E8 and CD68/CD206 expression by immunofluorescence staining in tissue microarrays constructed from renal (n = 190) and prostate (n = 274) cancer patient specimens." (PMID 35681775, 2022). "The pie chart showed that the heterozygous CNVs of all 6 genes (CD68, MRC1, CD8A, CD8B, CD163, and CLEC5A) was more frequent in various cancers." (PMID 35979347, 2022). "To analyze the intratumoral TME, we quantitatively compared iTAM cell counts using the CD68, CD163, PD-L1, CD20, and pan-CK markers in the three cancer subtypes." (PMID 36362023, 2022). "On the same tissue section, six cancer and immune markers were detected simultaneously, including a L-R pair (PD-1 and PD-L1), PanCK (epithelial cancer marker), CD8 (T cell marker), CD68 (Macrophage marker), FoxP3 (T regulatory cell marker)." (PMID 35967449, 2022). "Compared to CD68 and CD204, MAFB was markedly less expressed in AM and specifically expressed in ML and Mo in all data from normal lung and cancer tissues." (PMID 36077342, 2022). "Epithelial cell adhesion molecule (EpCAM)+ cancer cells (PD-L1− or T cell immunoglobulin mucin-3, TIM-3−), both PD-1 or TIM-3 positive CD8+ T cells, and CD14+CD68+CD163+TIM-3+ macrophages increased from the MPE1st to MPE2nd." (PMID 36293034, 2022). "GSCALite was utilized to identify the SNV frequency of all 6 genes (CD68, MRC1, CD8A, CD8B, CD163, and CLEC5A) in various cancers." (PMID 35979347, 2022). "SpatialVizScore generated immune cell infiltration maps using several cancer markers (pan-keratin & e-cadherin), stromal markers (SMA & collagen 1), and immune markers (CD8ɑ, CD68, CD163, CD206, and HLA-DR)." (PMID 36050391, 2022). "RT-qPCR showed the expression of CHI3L1, IL-10, RETNLB (Fizz1), and Arg1, to confirm the M2 macrophages The results showed that the expression level of both CD68 and CD206 were significantly increased in cancer tissues compared with paracancerous tissues." (PMID 35637970, 2022).
cancer (continued). "Even though CD68, CD163, and CD204 have been widely used to assess the severity and outcome of human cancers, opinion on what constitutes the definitive TAM marker remains controversial." (PMID 36077342, 2022). "Multiple immunofluorescence staining displayed the relationship between CD93 expression and CD8, CD68, and CD163 in these cancers." (PMID 36389798, 2022). "The co-expression of CD147 and macrophage markers CD68 and CD163 in pan-cancer was detected using multiplex immunofluorescence staining on tissue microarrays." (PMID 35464411, 2022). "In the present study, our data demonstrates that CD68 and SIRPα were more highly expressed in ICC patients compared with para-cancer controls." (PMID 35317832, 2022). "In cancer patients, number of TAM-expressed SRs (CD204, MARCO, CD68, LOX-1, Dectin-1, CD206, CXCL16, Stabilin-1, CD163, and RAGE) associates with negative and more sever prognosis." (PMID 36686729, 2022). "The binding of CD68 and PD-1 can induce M2 polarization of THP-1 derived macrophages and promote cancer growth." (PMID 34079767, 2021). "We then prepared paraffin-embedded cancer spheroids (PECS) and examined the presence of macrophages in spheroids by immunohistochemical staining of the pan macrophage marker CD68." (PMID 34451433, 2021). "Because both analyses showed that OLFML2B was positively correlated with macrophage content, we input cancer-related macrophage markers into the web tool “CellMarker” and obtained experimentally verified markers: CD14, CD68, CD163, CSF1R, ITGAM, and MRC1." (PMID 34868901, 2021). "The immunohistochemical analysis results revealed a marked accumulation of CD68 and CD3 positive cells around the invasive margin of the p16INK4A positive cancer." (PMID 33643790, 2021). "A strong correlation between CD68+ macrophages and the expression of GLUT1 and HK2 in cancer cells was found in patients with non-small-cell lung carcinoma (NSCLC)." (PMID 32486098, 2020). "For example, in human breast cancer tissues the positive correlation between CD68+ TAM infiltration and glycolytic enzyme expression GLUT1, GLUT3 and HK2 in cancer cells was demonstrated by immunostaining." (PMID 32486098, 2020). "The subgroups include proliferation genes (Ki67, STK15; Survivin, CCNB1, MYBL2), invasion genes (MMPP11, CTSL2), HER2 genes (GRB2, HER2), estrogen genes (ER, PGR, BCL2, SCUBE2), and other cancer related genes (GSTM1, CD68, BAG1)." (PMID 33665165, 2020). "For the myeloid-derived cancer cell lines, we identified specific surface markers (e.g., ITGAM, ITGAX, CD68, CD86) usually present on monocytes, neutrophils, and macrophages, positively contributing to the BAY-155, EPZ-5676, and Brequinar group." (PMID 31253180, 2019). "Like lymphoid cells, CD68+ and CD163+ macrophages were less abundant in RMS than in the most common cancers of adulthood." (PMID 31239476, 2019). "With regard to the density of immune cells around cancer cells on c-TMA cores, we noted a considerable variation from low density (“cold”) to high density (“hot”) for CD3, CD4, CD8, CD20, CD68, and MPO positive cells." (PMID 31817531, 2019). "It suggested that patients with high stromal infiltration of TILs, lower count of FOXP3+ Tregs and CD68+ Mφ in stromal site, and high expression of FOXP3 in cancer cells had longer survival of OS." (PMID 28029650, 2017). "Patients with high stromal infiltration of TILs, lower count of FOXP3+ Tregs and CD68+ Mφ in stromal site, and high expression of FOXP3 in cancer cells had longer OS." (PMID 28029650, 2017). "In multivariate Cox regression analysis, high count of intratumoral CD68+ Mφ [HR: 2.70 (1.00–7.31); p=0.050] and high expression of FOXP3 in cancer cells [HR: 0.29 (0.09–0.91); p=0.034] were independent prognostic factors for overall survival." (PMID 28029650, 2017). "In multivariate Cox regression analysis, high count of intratumoral CD68+ Mφ and high expression of FOXP3 in cancer cells were independent prognostic factors for overall survival." (PMID 28029650, 2017).
cancer (continued). "And high count of intratumoral CD68+ Mφ and high expression of FOXP3 in cancer cells were independent prognostic factors for overall survival." (PMID 28029650, 2017). "CD4+, CD8+, FOXP3+, CD68+, CD56+ and GZB+ cells were detected within cancer cell nests or the mesenchymal stroma." (PMID 28515351, 2017). "The present study demonstrated that CD68 and CD163 not only express in TAMs, but also in cancer cells." (PMID 26769084, 2016). "In the present study, we aim to investigate the incidence of CD68 and CD163 in relation to clinicopathological features and outcomes, then further insight into the interaction between TAMs and cancer cells undergoing EMT in OSCC progression." (PMID 26769084, 2016). "Similar to the pattern seen for CD4+ T-lymphocytes, CD68+ macrophages (TAMs) were observed predominantly in the superficial lamina propria of OLP and OLK tissues and/or the interstitial tissues of the cancer nests." (PMID 28053372, 2016). "CD68 has hitherto unknown functional significance in SFT cells, although it is worth noting that the acquisition of macrophage markers by tumoral cells in many other human cancers is often associated with a more malignant phenotype and generally correlates with a worse prognosis." (PMID 27304187, 2016). "The expression of CD68 and CD163 were not only confined to the infiltrating TAMs, but also presented in cancer cells." (PMID 26769084, 2016). "Considering that the cells express macrophage marker protein CD68, it is likely that SU3-ihCTCs are macrophage-derived cancer cells." (PMID 25483261, 2015). "We observed that the protein expression of the TAM markers CD68 and CD163 as well as the cancer stem cell (CSC) markers ALDH1, CD44, and SOX2 increased successively from the normal oral mucosa to OSCC." (PMID 24883329, 2014). "ix) Finally, localization of CD68+ (H2) and CD163+ (I2) macrophages close to carcinoma cells as well as high expression of FoxP3 (O2), L1CAM (P3) and vimentin (R), respectively, tended to be associated with higher grading (S)." (PMID 24797069, 2014). "With the use of these well recognized markers, it appeared that ATC tissue harbored only three types of cells: NOX2+ P22phox+ CD163+ CD68+ CD34− macrophages; NOX2− P22phox− CD163− CD68− CD34− cancer cells and NOX2− CD163− CD68− CD34+ blood vessel endothelium." (PMID 21811634, 2011). "Histopathology revealed infiltration of CD4+, CD8+ lymphocytes, and CD68+ macrophages without cancer cells." (PMID 41768084, 2026). "The contradictory findings in ESCA and LIHC, where CD68 expression did not consistently correlate with survival outcomes, further underscore the complexity of CD68’s role in cancer progression." (PMID 40918116, 2025). "The nuclear localization of CD68 observed in STAD but no other cancers suggests tissue-specific processing or function of this protein, potentially through differential cleavage or trafficking mechanisms." (PMID 40918116, 2025). "Levels of caspase-3 (an apoptotic marker), CD68 (a macrophage marker), and SPP1 (a cancer-associated fibroblast marker) showed nonstatistically significant decreasing trends, while other markers remained largely unchanged." (PMID 39946195, 2025). "The results indicated that regions with high HIF1A expression were correlated with an increased accumulation of SPP1+CD68+TAMs and HIF1A+ɑSMA+CAFs, suggesting the role of hypoxia in promoting the formation of the aggressive multicellular community and thus accelerating cancer progression in TNBC." (PMID 40432877, 2025). "The results revealed that mRNA expression of CD68 was higher in cancer tissues in ESCA (ns, no significant." (PMID 40918116, 2025). "Notably, the immune system-related CD68 and CD86, as well as the cancer-related ERBB2, have a relevance score of 0.8." (PMID 40593564, 2025).